PTPRK (protein tyrosine phosphatase receptor type K)
Diseases named in the same sentence as PTPRK in open-access papers (continued):
Sharing a sentence is not in itself a finding about the gene and the disease.
non-small cell lung carcinoma (1 paper, 2021). A group of at least three distinct histological types of lung cancer, including non-small cell squamous cell carcinoma, adenocarcinoma, and large cell carcinoma. "For example, hsa-miR-1260b is upregulated in non-small cell lung cancer (NSCLC) and promotes tumor growth, invasion, and metastasis by targeting PTPRK (Protein Tyrosine Phosphatase Receptor Type K) and SOCS6 (Suppressor of Cytokine Signaling 6)." (PMID 34150610, 2021).
ovarian tumor (1 paper, 2024).
subungual melanoma (1 paper, 2022). "Also, it has been reported that subungual melanoma harbors more distinct genomic alterations including CARD11, ARID2, ARID1A, ARID1B, PTPRB, and PTPRK genes, compared with acral melanoma." (PMID 35484605, 2022).
tumor (40 papers, 2011 to 2026). "We and others have identified numerous PTPRK substrates that have been implicated in PTPRK tumour suppressor function." (PMID 38904097, 2024). "PTPRK is a receptor tyrosine phosphatase that is linked to the regulation of growth factor signalling and tumour suppression." (PMID 38904097, 2024). "Several studies suggest the tumor suppressor role of PTPRK, further supported by its association with TGF-β and EGFR signaling pathways." (PMID 38999976, 2024). "For example, an SE event in protein tyrosine phosphatase receptor type K (PTPRK) is selected by both tumor-association and tumor-specificity screens, with the tumor-enriched isoform including a microexon." (PMID 37192158, 2023). "Our findings of abrogated junction organization, spheroid overgrowth and invasive behavior in PTPRK-deficient cells support its role as a tumor suppressor." (PMID 30924770, 2019). "PTPRK encodes for receptor-type tyrosine-protein phosphatase κ and is believed to mediate tumor suppressive function by interacting with and inactivating STAT3, as mentioned in the “Pro-proliferative signaling pathways” section." (PMID 30935402, 2019). "The loss of tumour suppressive function of PTPRK by truncation might therefore add increased selective pressure for this gene fusion beyond hyperactivation of Wnt signalling alone, by promoting EMT." (PMID 38904097, 2024). "So far, only little information is available about the precise biological functions of PTPRK, and its role in tumor-associated angiogenesis remains unclear." (PMID 38999976, 2024). "Indeed, PTPRK loss perturbs epithelial junction integrity and promotes invasive behaviors in spheroid cultures, consistent with its putative tumor suppressor role." (PMID 30924770, 2019). "In summary, decreased activity of PTPRK because of promoter inactivation or functional mutation was observed in different tumours and was mainly related to increased proliferation and migration of tumour cells since restoration of PTPRK had a tumour suppressive effect." (PMID 31027318, 2019). "Decreased levels of PTPRK expression or the loss of PTPRK activity due to mutation led to increased tyrosine-phosphorylation-based signalling, which is a major driving force in the development and progression of tumours." (PMID 28611294, 2017). "We hypothesized that alteration in PTPRK function contributes to the loss of contact inhibition of cell growth, facilitating proliferation and migration of tumor cells throughout the brain parenchyma." (PMID 23696788, 2013). "Our results suggest that tumor derived mutations of the PTPRK gene significantly alter PTPRK functionality, and thereby the PTPRK regulated signaling cascade by two ways: 1) altering its phosphatase activity; and, 2) altering post-translational processing of PTPRK." (PMID 23696788, 2013). "Additionally, in one of the patients with a STAT3 mutation, we detected a 9p copy number gain containing JAK2 and a point mutation in the protein tyrosine phosphatase (PTP) PTPRK, a commonly deleted tumor suppressor shown to negatively regulate STAT3 in NKTCL19." (PMID 29674644, 2018). "To investigate PTPRK signalling further, we subjected tumours to RNA sequencing (RNA-seq), histology and phosphotyrosine proteomic analyses." (PMID 38904097, 2024). "To investigate the role of PTPRK phosphatase activity in tumour suppression, we used a rescue approach in PTPRK KO HT29 xenografts." (PMID 38904097, 2024). "This was evident from fluorescence intensity line scans across junctions, where the PTPRK KO and PTPRK.RQ tumours show clear peaks of p120Cat-Y904 phosphorylation, whereas the PTPRK cells show no peak in fluorescence intensity." (PMID 38904097, 2024). "We also determined that PTPRK is a tumour suppressor both in mouse colon and in a HT29 xenograft model." (PMID 38904097, 2024). "To determine additional mechanisms of tumour suppression by PTPRK, we obtained quantitative tyrosine phosphoproteomes of WT and PTPRK KO xenograft tumour samples." (PMID 38904097, 2024).
tumor (continued). "We quantified 73 phosphosites, of which 11 were significantly differentially regulated in PTPRK KO and WT tumours." (PMID 38904097, 2024). "These images also revealed heterogeneity in expression of tGFP in PTPRK- and PTPRK.RQ-expressing tumours, compared to the PTPRK KO tumours, despite prior flow cytometry enrichment of tGFP-expressing cells." (PMID 38904097, 2024). "We next explored the role of PTPRK phosphatase activity in invasion, given the increased instances of invasive tumours in AOM–DSS-treated Ptprk−/− mice." (PMID 38904097, 2024). "PTPRK has been proposed to directly dephosphorylate numerous oncoproteins; however, we found that PTPRK can suppress tumour growth and EMT independently of its phosphatase activity." (PMID 38904097, 2024). "Prognostic factors in ovarian-originating PMP include not only CCR and PCI but also the involvement of genes like PTPRK and tumor markers like CA19-9." (PMID 39310419, 2024). "Consistent with previous reports, we show that PTPRK is a tumour suppressor in mouse colon; however, using xenografts, we demonstrate that this is surprisingly independent of PTPRK catalytic activity." (PMID 38904097, 2024). "PTPRK is a recurrent gene fusion with RSPO3, a Wnt pathway potentiator, particularly in serrated adenoma, a tumour type associated with a more mesenchymal phenotype." (PMID 38904097, 2024). "Protein tyrosine phosphatase receptor-type kappa (PTPRK) is a member of the R2B family of transmembrane receptor (R)PTPs that supports cell adhesion and has been implicated as a tumor suppressor." (PMID 36264065, 2022). "Other low frequency actionable fusions namely, AGK-BRAF, FIP1L1-PDGFRA, FNDC3B-PIK3CA, RET-NCOA4, SND1-BRAF, TMEM178B-MET, TMEM178B-BRAF, KANK1-NTRK3, EIF3E-RSPO2 and PTPRK -RSPO3 have been previously reported as rare fusions in tumours of other type." (PMID 35984852, 2022). "Disruption of PTPRK was shown to accelerate tumor growth through the phosphorylation of the cancer stem cell marker PROM1 and through activation of AKT signaling." (PMID 34585724, 2021). "Human PTPRK locates on the long arm of chromosome 6q22-23 and has been indicated as a tumor suppressor." (PMID 34646579, 2021). "Classic examples of this phenomenon are nucleophosmin 1 (NPM1) and PTPRK, putative tumor suppressor genes that are recurrently fused to ALK1 and RSPO3, respectively." (PMID 34585724, 2021). "Our discovery of PTPRK as a negative regulator of Wnt receptor turnover provides a rationale for its tumor suppressive function and reveals that in PTPRK-RSPO3 recurrent cancer fusions both fusion partners, in fact, encode ZNRF3 regulators." (PMID 31934854, 2020). "Receptor‐type protein tyrosine phosphatase κ (PTPRK) is considered to be a candidate tumor suppressor." (PMID 30947381, 2019). "The receptor-type tyrosine-protein phosphatase κ (PTPRK) is a candidate tumor suppressor involved in the tumorigenesis of various organs." (PMID 30838170, 2019). "Several of the PTPRK substrates identified here have been linked to cancer, including PARD3 loss-of-function in invasion, and oncogenic and tumor suppressive roles for p120Cat." (PMID 30924770, 2019). "Our findings show PTPRK as an important tumor suppressor and a potential target gene for diagnosis and therapies in NSCLC." (PMID 30838170, 2019). "Restoration of PTPRK suppressed tumor cells proliferation and reduced migration and invasive ability of tumor cells." (PMID 31027318, 2019). "In summary, by defining the substrate repertoire of human PTPRK, we reveal mechanistic insight into its putative tumor suppressor role through its control of cell-cell junctions and suppression of EMT." (PMID 30924770, 2019). "PTPRK has also been shown to act as a tumor suppressor in central nervous system lymphomas, CRC, and prostate cancer." (PMID 30208623, 2018).
tumor (continued). "Several PTPs have been extensively studied and identified as tumor-suppressor genes, such as phosphatase and tensin homolog (PTEN), protein tyrosine phosphatase kappa (PTPRK), and Fas-associated phosphatase 1 (FAP-1)." (PMID 29278368, 2017). "The PTPRK gene is located in a putative tumour-suppressor region of the human genome, on the long arm of chromosome 6." (PMID 28611294, 2017). "Further, inactivation of PTPRK has been recently observed in several tumors, indicating and independently confirming its tumor suppressive role." (PMID 23696788, 2013). "Transcriptome analysis of the compound 2a-treated cancer cells suggested that the downregulation of protein tyrosine phosphatase receptor type K (PTPRK) serves as a biomarker for monitoring anti-tumor effects of RM." (PMID 22494416, 2012). "Taken together, these data indicate that PTPRK suppresses tumour growth and invasion in vivo." (PMID 38904097, 2024). "This is consistent with both PTPRK and PTPRK.RQ suppressing tumour growth and invasion." (PMID 38904097, 2024). "Consistent with a tumour suppressor function, we found that PTPRK KO xenografts had a higher growth rate than WT xenografts, and that this could be fully rescued by re-expressing PTPRK." (PMID 38904097, 2024). "To evaluate the role of PTPRK phosphatase activity on tumour growth we generated xenografts." (PMID 38904097, 2024). "EBV+ cHL tumor cells demonstrated more frequent downregulation of PTPRK than EBV− cHL tumor cells." (PMID 37046794, 2023). "PTPRK was reported to inhibit tumor progression by directly targeting STAT3 activation." (PMID 36341348, 2022). "Furthermore, inactivation of PTPRK has been recently reported in several tumors, indicating that it can also act as a tumor suppressor by inhibiting cell cycle progression." (PMID 34646579, 2021). "Among these, PTPRK, PTPRM, and PTPRT are implicated as tumor suppressors, raising the possibility that they may also regulate ZNRF3 in certain cell types." (PMID 31934854, 2020). "This supports the role of PTPRK-mediated dephosphorylation of this site in tumor suppression." (PMID 30924770, 2019). "Our conclusions have implications not only for understanding PTP biology and cell-cell junction phosphoregulation, but also provide molecular insight into how PTPRK might function as a tumor suppressor." (PMID 30924770, 2019). "Thus, identifying PTPRK substrates provides insight into its downstream signaling and a potential molecular explanation for its proposed tumor suppressor function." (PMID 30924770, 2019). "Germline loss of chromosome 6q22.33, which harbors two potential tumor suppressor genes, PTPRK and LAMA2, was also identified; this may increase tumor predisposition further." (PMID 26432421, 2015). "Moreover, overall survival analysis identified PTPRK as a tumor suppressor candidate with prognostic, therapeutic and clinical predictive values." (PMID 23696788, 2013). "Our results provide a rationale how PTPRK may function as a tumor suppressor in Wnt-ON tumors." (PMID 31934854, 2020). "Notably, several lines of evidence indicate that PTPRK acts as a putative tumor suppressor." (PMID 30947381, 2019). "In these gene fusions, the signal sequence of PTPRK is fused to RSPO3, reducing PTPRK and leading to elevated RSPO3 protein levels, which in transgenic mouse models are sufficient to drive tumor initiation." (PMID 31934854, 2020). "PTPRK dephosphorylates and inactivates oncogenic proteins such as STAT3, EGFR and CD133, is frequently downregulated in human cancers, and is considered a tumor suppressor." (PMID 31934854, 2020). "The identification of potential tumor suppressor genes, PRDM1 and PTPRK, and pro-survival signaling via MYC and NF-KB are of particular importance as key events in ENKTL pathogenesis." (PMID 29966370, 2018).
tumor (continued). "PTPRK can directly dephosphorylate EGFR during both basal- and ligand-stimulated EGFR phosphorylation, and it can contribute to tumor suppression through its negative regulation of EGFR signaling." (PMID 30208623, 2018). "RNA interference of PTPRK accelerates cell cycle progression, enhances response to EGF, and abrogates TGF-β-mediated antimitogenesis, suggesting a tumor-suppressive role of PTPRK." (PMID 21637380, 2011). "PTPRK has previously been predicted to regulate a hybrid EMT state, which could be optimal for tumour metastasis." (PMID 38904097, 2024). "Further investigation of the non-catalytic functions of PTPRK is required to elucidate its mechanisms of tumour suppression." (PMID 38904097, 2024). "First, we cultured PTPRK KO and WT HT29 cells as tumour spheres." (PMID 38904097, 2024). "Tumour growth rate inversely correlated with both PTPRK and PTPRK.RQ expression levels, suggesting that PTPRK tumour suppression is at least in part independent of phosphatase activity." (PMID 38904097, 2024). "Intriguingly, our previous studies revealed that a receptor tyrosine phosphatase PTPRK removes the phosphorus groups from these tyrosine residues of CD133, attenuates CD133‐mediated xenograft tumor growth of colorectal cancer cells in nude mice and stimulates anti‐tumor drug‐induced cell death." (PMID 33720534, 2021). "The present study showed that knockdown of PTPRK accelerated xenografted tumor growth of SW480/CD133 cells but not of CD133‐negative SW480/eGFP cells accompanied by a larger amount of p‐AKT." (PMID 30947381, 2019). "Copy number analyses have highlighted potential tumor suppressor genes such as PR Domain Zinc Finger Protein 1 (PRDM1) and protein tyrosine phosphatase kappa (PTPRK) while next generation sequencing studies have identified recurrently mutated genes in pro-survival and anti-apoptotic pathways." (PMID 29966370, 2018). "A number of genes demonstrated reduced copy number and expression in KRAS mutant tumours, including putative tumour suppressor genes (FOXO3, EXTL2, PPP2R1B), negative regulators of the receptor tyrosine kinase oncogenic pathways (PTPRK, DGKZ, NCAM1), and negative regulators of Ras (EPHB2)." (PMID 21385341, 2011). "Further investigation on PTPRK, a Smad target gene indentified in this study, indicates that while TGF-β upregulates PTPRK expression in both tumor and nontumor mammary cells, HER2 overexpression downregulates PTPRK." (PMID 21637380, 2011). "Thus, both tumour growth and invasion suppression by PTPRK appear to be independent of catalytic activity." (PMID 38904097, 2024). "Furthermore, as reported in other tumors types, upregulation of DAB2, RND3, TMEM97, CSE1L, MYO1C, and PTPRK have been shown to suppress or functionally redistribute E-cadherin expression in cancer cells, resulting in EMT, increased invasion, advanced tumor stage and poor patient survival." (PMID 27863424, 2016). "However, other modes of action of PTPRK, such as dephosphorylating other signaling factors like β-catenin, EGFR, or STAT3, or cell junction proteins, may also contribute to its tumor-suppressive function." (PMID 31934854, 2020).